TIMP1 (TIMP metallopeptidase inhibitor 1)
Diseases named in the same sentence as TIMP1 in open-access papers (continued):
Sharing a sentence is not in itself a finding about the gene and the disease.
glaucoma (20 papers, 2008 to 2026). Increased pressure in the eyeball due to obstruction of the outflow of aqueous humor. "On multiple regression analysis, it was revealed that the presence of DM and preoperative glaucoma were independent risk factors affecting TIMP1 levels." (PMID 41009516, 2025). "The presence of preoperative glaucoma significantly increased the levels of TIMP1 (176,623.6 pg/mL, p = 0.018)." (PMID 41009516, 2025). "Second, among the 13 upregulated markers, many were already reported in the AH of patients with glaucoma (e.g., TIMP1, FCGBP)." (PMID 37895034, 2023). "In summary, our study showed that the expression levels of TNF-α, IL-2, IL-6, IL-8, BDNF, MMP-2, MCP-1, VEGF, IFN-γ, LT-α, bFGF, PDGF-AA, and TIMP-1 were different among the 3 types of glaucoma." (PMID 36254076, 2022). "So far, Cxcl10, Myc, Timp1, Serpina3n, and Ednrb have been reported to be upregulated in retinas after light damage or other injury/diseases models such as retinal detachment, glaucoma, or retinal ischemia-reperfusion." (PMID 33614628, 2020). "The integrated system significantly reversed glaucoma-induced changes in TNF-α, IL-8, MYOC, NRF2, TIMP1, and IL-1β levels, resembling those of the healthy group." (PMID 40643885, 2026). "The levels of TNF-α, MMP-2, MCP-1, IFN-γ, TIMP-1, IL-6, IL-8, VEGF, and LT-α were different among the three types of glaucoma." (PMID 36254076, 2022). "We found that the levels of TIMP1 and MMP2 were higher in patients with glaucoma." (PMID 41009516, 2025). "MMP2, MMP3, and TIMP1 were also detected in higher, but not significantly different, amounts in aqueous samples of primary open-angle glaucoma eyes." (PMID 41009516, 2025). "Furthermore, TIMP1 and MMP2 levels were significantly elevated in patients with preoperative glaucoma." (PMID 41009516, 2025). "In studies focusing on prostaglandin analogue-treated glaucoma patients, IL1B, IL6, and matrix metallopeptidases 1, 3, and 9 (MMP1, MMP3, and MMP9) were seen to be increased, while TIMP metallopeptidase inhibitors 1 and 2 (TIMP1 and TIMP2) were decreased." (PMID 35897711, 2022). "The increase in TIMP1 and TIMP2 may lead to the inhibition of MMP2 activity and contribute to the IOP of primary open-angle glaucoma." (PMID 33195434, 2020). "TIMPs were increased in the plasma of untreated children with JIA, have been associated with levels of matrix metalloproteinase (MMP)-1, MMP-3, and TIMP1 in paired serum and synovial fluid also in those with JIA, and were found in AqH of patients with glaucoma." (PMID 30327966, 2018). "Differential expression of motility genes, including capping protein G (CAPG) and transforming growth factor beta-induced (TGFBI), was consistent with the reactive, migratory astrocyte phenotype characteristic of glaucoma, as were ECM remodeling genes, such as GPNMB and TIMP1." (PMID 18822132, 2008). "Moreover, on the molecular level, LUT-EX@MN arrays reversed glaucoma-induced biochemical changes, such as the inflammatory markers; TNF-α, IL-8, and IL-1β, glaucoma-related biomarkers; MYOC, NRF2, and TIMP1 and the activity of glutathione peroxidase to levels comparable to healthy controls." (PMID 40643885, 2026). "They found that MMP2, MMP3, TIMP1, and TIMP2 were detected at significantly higher concentrations in aqueous samples from eyes with pseudoexfoliation with and without glaucoma compared with cataractous eyes." (PMID 41009516, 2025).
rheumatoid arthritis (20 papers, 2005 to 2025). A chronic, systemic autoimmune disorder characterized by inflammation in the synovial membranes and articular surfaces. "TIMP1 has been implicated in the patho-physiology of a number of inflammatory diseases including psoriasis and rheumatoid arthritis." (PMID 23555662, 2013). "One study performed by Onodera and colleagues previously reported that MIF can influence the mRNA levels of TIMP-1 in a dose-dependent manner in rheumatoid arthritis synovial fibroblasts." (PMID 37508563, 2023). "The inhibition of MMP’s by TIMP1 should theoretically reduce destruction of the inflamed joint and yet disease severity in Rheumatoid arthritis positively correlates with serum TIMP1 concentration." (PMID 23555662, 2013). "Pro-inflammatory effects of TIMP-1 have also been suggested in in vivo models of rheumatoid arthritis." (PMID 16316466, 2005). "TIMP-1 mRNA has been previously identified in OA and rheumatoid arthritis." (PMID 24132152, 2013). "Hegemann and colleagues demonstrated in canine rheumatoid arthritis that the amount of TIMP-1 was not sufficient to block the increased MMP-3 activity." (PMID 15642138, 2005).
non-small cell lung carcinoma (19 papers, 2009 to 2025). A group of at least three distinct histological types of lung cancer, including non-small cell squamous cell carcinoma, adenocarcinoma, and large cell carcinoma. "In several cancers including non-small cell lung cancer, high serum levels of TIMP-1 have been associated with poor prognosis." (PMID 29507665, 2018). "TIMP-1 expression was found to correlate positively with cancer progression, such as myeloma, non-small cell lung cancer and endometrial carcinoma." (PMID 35830566, 2022). "In patients with non-small cell lung cancer who underwent surgical resection with curative intent, postoperative TIMP-1 has been reported as an independent predictor of prognosis." (PMID 24457057, 2014). "Recently it has been shown that the over expression of TIMP1 was an independent prognostic marker in patients with non-small cell lung carcinoma." (PMID 19347046, 2009). "Additionally, the secreted nature of TIMP1 presents it as a promising serum-free prognostic marker for OC, similar to its role in non-small-cell lung cancer, where plasma TIMP1 levels were able to discriminate between cancer patients and healthy controls." (PMID 40427104, 2025). "However, a recent paper has demonstrated TIMP-1 mediated chemoresistance in a non-small cell lung carcinoma model via induction of IL-6 secretion." (PMID 33023532, 2020). "Additionally, it was reported that higher expression of TIMP-1 occurs in adenocarcinoma cells related to the higher stromal intensity of squamous cell carcinoma and non-small cell lung cancer." (PMID 31998645, 2019). "The presented study aims to assess the change, during one year after diagnosis, in the expression of TIMP1 mRNA and two metalloproteinases involved in the neoplastic process, the activity of which is inhibited by TIMP-1 in non-small-cell lung cancer." (PMID 37509417, 2023). "Elevated tissue inhibitor of metalloproteinase-1 (TIMP-1) is a negative prognosticator in non-small cell lung carcinoma NSCLC patients." (PMID 31443242, 2019). "Altogether, this evidence suggests that TIMP-1 could have a role in the generation of PT-resistance, also in EOC, as previously reported for non-small cell lung cancer cells." (PMID 31861382, 2019).
colitis (18 papers, 2013 to 2025). Inflammation of the colon. "We also checked the diagnostic value of serum TIMP-1 in distinguishing children with right-sided (E3, E4) colitis from those with left-sided (E1, E2) colitis." (PMID 35566780, 2022). "uPA-mediated signaling (Timp1-, Mmp3-, Mmp9-centered sub-networks) controls macrophage phagocytosis in intestinal inflammation, and uPA receptor deficiency leads to marked aggravation of experimental colitis in mice." (PMID 36901742, 2023). "Pre-treatment with recombinant TIMP-1 of mice with experimental colitis reduced the mucosal pathology while splenocytes from pretreated mice produced less TNF-α and more IL-10 than untreated mice following stimulation with anti-CD3." (PMID 40565065, 2025). "Specifically, in TNBS-induced colitis, Cd44, Numa1, S100a8, S100a9, Timp1 and Xbp1 were more highly expressed, while Cidec and Rag1 were less expressed." (PMID 38778086, 2024). "Consistent with previous work, in the DSS mouse model, the expression levels of Cd44, S100a8, S100a9 and Timp1 were greater in the mice with colitis; while the expression level of Ndrg1 was lower in the mice with colitis." (PMID 38778086, 2024). "Our analysis revealed some diagnostic value of both serum TIMP-1 and MMP-9 in distinguishing children with left-sided colitis from those with right-sided colitis." (PMID 35566780, 2022). "Colitis mouse studies also showed that the expression of TIMP1 was increased during the active period of inflammation and decreased significantly during the recovery period." (PMID 36419192, 2022). "Our findings indicated that the overexpression of α-SMA, Collagen I, TGF-β1, Collagen III, pSMAD3, pSMAD2 and TIMP1 in DSS-induced colitis was downregulated by ME treatment." (PMID 34456904, 2021). "The expressions of ICAM-1, IL-1β, IL-16, CXCL10, MCP-1, CXCL9, CXCL12, and TIMP-1 were greatly reduced in MSC-EX-treated colitis group compared with those in the PBS-treated colitis group." (PMID 28842625, 2017). "The activity of MMP1, 3 and 9 is controlled by tissue inhibitor of metalloproteinase (TIMP-1), the expression of which is also increased in colitis." (PMID 23700416, 2013). "Furthermore, Timp1, which encodes a TIMP that preferentially inhibits MMP-1, -3, -7, and -9, is overexpressed in colitis and CAC, suggesting tight regulation of MMP activity in both disorders." (PMID 38288108, 2023). "Additionally, TIMP-1 is expressed in colitis lesions and is involved in the production of the proinflammatory cytokine IL-10." (PMID 37375714, 2023). "Interestingly, when comparing right-sided (E3, E4) colitis with left-sided (E1, E2) colitis, the concentration of TIMP-1 in serum was significantly higher in patients with right-sided lesions (median 215.6 ng/mL vs. 157.6 ng/mL, p = 0.006)." (PMID 35566780, 2022). "Cytokine protein arrays showed that the levels of several cytokines, including sICAM-1, IL-1β, IL-16, CXCL10, MCP-1, CXCL9, and TIMP-1, were upregulated (≥50-fold) in the colitis-induced PBS-treated group compared with those in the normal healthy control group." (PMID 28842625, 2017). "The expression of TIMP-1 was significantly upregulated, and MMP2/9 were significantly downregulated in the colonic tissue of mice with TNBS-induced colitis." (PMID 35002710, 2021). "We have also reported the alleviated mucosal and neuronal damage in recurrent colitis and the development of intestinal strictures due to high MMP9 (matrix metallopeptidase-9) and lower TIMP1 (TIMP metallopeptidase inhibitor 1) expression in the colon." (PMID 31010141, 2019). "Finally, the expression of the revealed hub genes related to acute colitis (C3, Tyrobp, Mmp3, Mmp9, Timp1) and CAC (Timp1, Adam8, Mmp7, Mmp13) was validated by qRT-PCR in the colon tissue of mice with acute colitis and colitis-driven adenomas." (PMID 36901742, 2023). "In addition, the antifibrotic effects of glutamine in TNBS induced colitis was partly attributed to abrogation of the overexpression of TGF-β, phosphorylated Smad3, and TIMP-1." (PMID 25948887, 2015).
colitis (continued). "Indeed, upregulation of ALK5 and TIMP-1, phosphorylation of Smad2 and Smad3 proteins, and increased intestinal wall collagen deposition were found in anaerobic bacteria- and TNBS-induced colitis." (PMID 25948887, 2015). "Interestingly, the tissue inhibitor of matrix metalloproteinase-1 (Timp1) was also detected as a hub gene specific to both acute colitis and CAC and tightly interconnected with MMPs module, which clearly indicated the importance of Timp1/MMPs balance in colitis-induced tumorigenesis." (PMID 36901742, 2023).
coronary artery disease (18 papers, 2009 to 2025). "While all mice harboured coronary disease, atherosclerotic burden was reduced in Mmp7-deficient and Mmp12-deficient mice and increased in Timp1-deficient animals, compared to relevant controls." (PMID 34848763, 2021). "Disease progression in coronary artery disease was previously associated with an increasing MMP-9/TIMP‐1 ratio in circulating CD14+ monocytes." (PMID 31932967, 2021). "Circulating TIMP-1 levels have been associated with poor prognosis in a community-based cohort of elderly men risk, patients with coronary artery disease, and in different cancer types, such as lung breast colorectal and gastric cancer." (PMID 26162891, 2015). "Previously, there have been found an association between circulating TIMP-1 levels and poor prognosis in elderly men, patients with coronary artery disease, patients with different types of cancer, and patients with severe trauma brain injury." (PMID 26162891, 2015). "Furthermore, higher TIMP‐1 levels were reportedly associated with cardiovascular events in a Chinese follow-up study of patients with coronary heart disease." (PMID 31932967, 2021). "Identifying the effects of the causative factors for the secretion of MMP-9 and TIMP-1 by VSMC may facilitate the understanding of the pathogenesis of coronary heart disease." (PMID 25405958, 2015). "From the systematic search we have carried out, few studies found that TIMP-1 and 2 significantly decreased in coronary artery disease (CAD) patients compared to control, while they increased in control subjects." (PMID 39195176, 2024). "In accordance, significantly higher levels of plasma TIMP-1 have been previously observed in two studies in type 2 diabetic patients with a history of coronary artery disease." (PMID 25848912, 2015). "In a publication from the ARIC group, plasma levels of TIMP-1 and MMP-1 were unrelated to increased risk of coronary artery disease whereas in Framingham, plasma TIMP-1 levels were positively associated with cardiovascular incidence and death." (PMID 23554968, 2013). "In one study, ST-elevation myocardial infarction (STEMI) patients showed higher serum MMP-9 and MMP-9/TIMP-1 values compared to subjects without coronary artery disease (CAD), but they had no prognostic value in a 2-year follow-up." (PMID 29349668, 2018).
periodontal disease (18 papers, 2013 to 2024). "Among the top five hub genes highlighted in this interactome are IL17RC, CCN2, BMP7, TPM1, and TIMP1, all of which have been implicated in periodontal disease in conjunction with peri-implant disease." (PMID 39659491, 2024). "Our analysis revealed a co-expression network comprising 216 genes, including prominent hub genes such as IL17RC, CCN2, BMP7, TPM1, and TIMP1, which are implicated in periodontal disease." (PMID 39659491, 2024). "The authors reported that higher MMP-3 and TIMP-1 levels correlated positively with clinical parameters and were related to significantly greater risk of progression of periodontal disease." (PMID 36167610, 2023). "The purpose of the present study was to evaluate TIMP-1 as a salivary biomarker and its diagnostic significance in periodontal disease." (PMID 26464855, 2014). "The study identified 216 genes, with top hub genes like IL17RC, CCN2, BMP7, TPM1, and TIMP1 involved in periodontal disease." (PMID 39659491, 2024). "Three studies revealed that TIMP‐1 levels in oral fluids were significantly decreased in periodontal disease." (PMID 34850390, 2022). "Because not all these items had a relation to the focus of this study, TIMP‐1 as biomarker for periodontal disease, the outcome of these items weighted less in the assessment of study quality." (PMID 34850390, 2022). "TIMP-1 in saliva has previously been investigated as a biomarker for periodontal disease, and thereby a significantly lower TIMP-1 saliva concentration was detected." (PMID 36551979, 2022). "In this context, the aim of this systematic review was to analyze the validity of TIMP‐1 solely as a biomarker to diagnose periodontal disease in saliva and gingival crevicular fluid (GCF)." (PMID 34850390, 2022). "It is believed that the MMP-8 level and the MMP-8/TIMP-1 ratio strongly correlate with clinical parameters in the periodontal disease such as the depth of gingival pockets or the bleeding in probing." (PMID 31781639, 2019). "Second, since the imbalance between MMP-8 and its inhibitor TIMP-1 is considered to initiate periodontal disease, we think that it would be much valuable to perform further analyses on both MMP-8 and TIMP-1 in the future." (PMID 29587716, 2018). "TIMP-1 was demonstrated to be the major inhibitor of MMPs in gingival tissues of patients with periodontal disease." (PMID 24886536, 2014). "ELISA was the method used to evaluate salivary TIMP-1 levels in this study, with the intention to provide an economical alternative for periodontal disease assessment." (PMID 26464855, 2014). "The high SD values indicate that there is a large variation in TIMP‐1 concentration in both the periodontal disease group as in the control group, which suggests that other confounders might be present." (PMID 34850390, 2022). "However, the included studies on the potential use of TIMP‐1 as biomarker for periodontal disease varied greatly in results." (PMID 34850390, 2022). "In particular, TIMP‐1 is a frequently studied biomarker for periodontal diseases." (PMID 34850390, 2022). "Therefore, it is possible that the contribution by elevated TIMP‐1 levels in serum of RA, osteoporosis, exercise, and overweight/obese individuals outweighs the decreased salivary TIMP‐1 values associated with periodontal disease." (PMID 34850390, 2022). "In conclusion, TIMP‐1 is no reliable biomarker for screening and diagnostic purposes of periodontal disease." (PMID 34850390, 2022). "Of 597 patients suffering from periodontal disease salivary TIMP‐1 levels were measured." (PMID 34850390, 2022). "By testing the MMP-8 and TIMP-1 levels and the MMP-8/TIMP-1 ratio, individuals with periodontal disease may be differentiated from subject in the control group." (PMID 31781639, 2019). "In addition, it was reported that there is a substantial increase in the concentrations of MMP-3 and decrease of TIMP-1 in gingival crevicular fluid (GCF) in periodontal disease." (PMID 29054963, 2017).
periodontal disease (continued). "However, so far the diagnostic value of TIMP‐1 in periodontal disease has not been systematically reviewed." (PMID 34850390, 2022). "Therefore, we hypothesized that the reduction of dental plaque by CHX mouthrinse might affect the GCF MMP-8 and TIMP-1 levels, which is known to act as crucial mediators in inflammatory process of periodontal diseases." (PMID 24886536, 2014). "This is confirmed by the results presented in this systematic review with meta‐analysis in which no significant changes in TIMP‐1 concentrations in oral fluids were found between periodontal disease and healthy individuals." (PMID 34850390, 2022). "However, we did not measure a difference for either TIMP-1 and fHsp70, between subjects with previous periodontal disease and those with no history of periodontal disease." (PMID 36551979, 2022). "Negative correlations were shown between periodontal disease severity and GCF TIMP-1 and -2 levels, together with a positive correlation to MMP-8 and -9 activities." (PMID 33143325, 2020).